RN7SL122P (RNA, 7SL, cytoplasmic 122, pseudogene)
Gene: Miscellaneous RNA gene on chromosome 1 (32,457,835 to 32,458,135, forward strand). Ensembl gene ENSG00000263529.
Homologues: Orthologues: chimpanzee Metazoa_SRP (99% identical), macaque Metazoa_SRP (87% identical), dog Metazoa_SRP (61% identical). Paralogues in human: RN7SL1 (84% identical), RN7SL2 (84% identical), RN7SL220P (84% identical), RN7SL3 (84% identical), RN7SL126P (83% identical), RN7SL709P (82% identical), RN7SL127P (81% identical), RN7SL333P (81% identical), RN7SL665P (81% identical), RN7SL743P (81% identical), RN7SL296P (81% identical), RN7SL44P (81% identical), and 700 more.